SRY (sex determining region Y)
Diseases named in the same sentence as SRY in open-access papers (continued):
Sharing a sentence is not in itself a finding about the gene and the disease.
Nephroblastoma (1 paper, 2017). An embryonal neoplasm characterized by the presence of epithelial, mesenchymal, and blastema components. "The SRY gene was found in 5/8 (62.5%) rats from the group treated with iPSs and, coincidentally, all 5 animals had nephroblastomas." (PMID 28845162, 2017).
osteoarthritis (1 paper, 2019). A noninflammatory degenerative joint disease occurring chiefly in older persons, characterized by degeneration of the articular cartilage, hypertrophy of bone at the margins and changes in the synovial membrane. "Double staining of SRY and c-Myb using human tissue samples from male patients with osteoporotic fractures and osteoarthritis or no such disorder (i.e., controls) showed double-positive and single-positive cells." (PMID 31409771, 2019).
Osteopenia (1 paper, 2019). Osteopenia is a term to define bone density that is not normal but also not as low as osteoporosis. "Hormonal replacement therapy is necessary to assure a normal menstrual cycle and secondary sex characteristics and to reduce the risks of osteopenia, which suggests the importance of SRY in normal bone development and hormonal status." (PMID 31409771, 2019).
Thyroid adenoma (1 paper, 2012). The presence of a adenoma of the thyroid gland. "SRY gene was searched in 10 thyroid adenoma specimens (6 in paraffin and 4 frozen)." (PMID 22577597, 2012). "None of the 6 paraffin-embedded thyroid adenoma was positive for the SRY gene analysis, whereas 1 out of 4 frozen samples with thyroid nodules showed male cells." (PMID 22577597, 2012).
type 2 diabetes mellitus (1 paper, 2021). A type of diabetes mellitus that is characterized by insulin resistance or desensitization and increased blood glucose levels. "Hsa-let-7d-5p, hsa-mir-29c-3p and SRY (sex-determining region Y) have been reported to be associated with type 2 diabetes mellitus, but these genes might be novel target for GDM." (PMID 33890634, 2021).
cancer (24 papers, 2012 to 2025). A tumor composed of atypical neoplastic, often pleomorphic cells that invade other tissues. "Sex determining region Y (SRY)-box 2 (SOX2) is a marker of cancer stem-like cells (CSCs) and is associated with the proneural molecular subtype of GBM." (PMID 31358880, 2019). "Indeed, we found that TSPYL2 accumulation, in male cancer cells, is prevented by the Y-encoded protein SRY, which modulates MDM2 protein levels." (PMID 36918555, 2023). "Conversely, SRY overexpression in the female cancer cell lines U2OS and HeLa and in the male normal ARPE-19 cells is sufficient to reduce the accumulation of TSPYL2 at both 24 and 48 h after etoposide treatment." (PMID 36918555, 2023). "Deregulated expression of SRY has been found in male tumors where it demonstrated oncogenic properties, possibly contributing to the sexual dimorphism present in certain types of cancer." (PMID 36918555, 2023). "This platinated distorted DNA is also a good substrate for other proteins, such as HMG-B4 and other transcription factors containing HMG-boxes such as SRY, LEF-1 or TOX4 that are associated with cancer stemness, and targets for cancer treatment." (PMID 29921764, 2018). "Of which, the cancer stem cell markers such as SRY (sex determining region Y)-box 2 (SOX2) and Nestin have gotten researchers interested." (PMID 27150062, 2016). "HDAC3 is involved in the regulation of cancer-associated cellular process like apoptosis, and is also important in the regulation of cancer-associated transcription factors functions, including PCAF, SRY, NF-kB and STAT proteins." (PMID 26405459, 2015). "The sex-determining region Y (SRY) associated high-mobility group (HMG) Box (SOX) transcription factors are pluripotency associated stem cell factors involved in various process during embryogenesis and are aberrantly expressed in many cancers." (PMID 37298099, 2023). "Moreover, transcriptional control of miR-34a by HOTAIR influenced SOX2 (SRY (sex determining region Y)-Box 2), an essential stemness factor regulating the self-renewal capacity of cancer stem cells." (PMID 37175800, 2023). "Since loss of TSPYL2 accumulation in male cancer cells is not due to reduced transcription, we hypothesized that SRY may regulate TSPYL2 levels indirectly or through a transcription-independent mechanism." (PMID 36918555, 2023). "Unraveling the potential connection between SRY/Sox proteins, ceramide production, and PP2A activation in cancer will deepen our understanding of cancer development, offering potential for refining therapy strategies." (PMID 39915438, 2025). "Nevertheless, we noticed that, in MG-63 cells, SRY depletion by siRNA transfection restores the pattern of TSPYL2 accumulation observed in normal and female cancer cells." (PMID 36918555, 2023). "Among these genes, SRY (sex determining region Y)-box 17 (SOX17) is a transcription factor important for esophagus tissue development and is hypermethylated in human cancers." (PMID 36497337, 2022). "With progress of cancer biology, a number of genes have been investigated for predicting prognosis of NSCLC, such as cancer stem cell markers SRY (sex determining region Y)-box 2 (SOX2) and Nestin." (PMID 27150062, 2016). "Importantly, at least in cancer cells, this TSPYL2 function is sex-specific since expression of the male-specific gene SRY prevents TSPYL2 accumulation in male cancer cells." (PMID 36918555, 2023). "In addition, SOX10, a transcription factor of the sex determining region Y (SRY)-related high motility group (HMG)-box gene family, playing an important role in cancer progression, including tumorigenesis, changes in the tumor microenvironment, and metastasis." (PMID 33941222, 2021). "Moreover, the expressions of IL-1α, SRY, Oct4, IL-6, and TGF-β in BMSCs were markedly increased by cancer cell-derived EVs." (PMID 34746322, 2021).
cancer (continued). "Furthermore, bioinformatic analysis of miR‐34a targets in various cancers identifies numerous target genes such as Jagged 1 (JAG1), CD44, SRY (sex determining region Y)‐box 4 (SOX4), Notch homolog 2 (NOTCH2), Matrix metallopeptidase 9 (MMP9), Interleukin 6 (IL‐6), and SMAD family member 4 (SMAD4)." (PMID 40336533, 2025). "In addition to CD44, Nanog Homeobox (Nanog), SRY (Sex Determining Region Y)-Box 2 (SOX2), and Octamer-Binding Transcription Factor 4 (Oct4) play crucial roles in maintaining cancer stemness progression and the poor prognoses in cancer patients." (PMID 38612715, 2024).
tumor (23 papers, 2009 to 2025). "Inconsistently, extreme downregulation of chromosome Y has been noted as a feature independent of age, similarly to our results, where loss of SRY and downregulated expression in tumor tissue were age independent." (PMID 33807423, 2021). "Moreover, except SRY, all analyzed genes were associated with a different tumor composition and immunological profiles." (PMID 38132438, 2023). "In addition, an inverse association between MEIS1 and SRY (sex determining region Y)‐box 2 (SOX2) in ESCC tumor samples was reported." (PMID 31090196, 2019). "Understanding the immunoregulatory role of SRY provides valuable insights into the sex-specific tumor microenvironment and its impact on HCC progression." (PMID 40438106, 2025). "NR5A1 regulates other target genes, such as SRY, responsible for testicular differentiation, WT1, and DHH, associated with gonadal abnormalities and increased risk of tumor." (PMID 41303802, 2025). "Our results clearly point to SOX6, SOX8 and SRY as factors which are characteristic for a tumor tissue." (PMID 38132438, 2023). "MALAT1 is a tumor promoter involved in the maintenance of stemness, acting upon the Wnt pathway, SRY (sex-determining region Y)-related HMG (high mobility group)-box transcription factor 2 (SOX2), and Nestin." (PMID 36980238, 2023). "To further explore the role of SRY in tumor development, we employed GSEA and tested TCGA gene expression data in all the major data set collections (H-C8) provided from the Molecular Signatures Database (MSigDB)." (PMID 33807423, 2021). "This then being in line with our results from the tumor-matched blood samples showing that SRY deletions are more common in tumor tissue than in the blood of the GBM patients." (PMID 33807423, 2021). "Another circRNA called Sry (sex-determining region Y) was reported to serve as a sponge for miR-138, thus regulating the invasion, development and metastasis of tumor cells." (PMID 30157902, 2018). "S100P, CXCL11, and SRY (Sex Determining Region Y)-Box 11 (SOX11) display higher expression in tumor samples." (PMID 27857161, 2016). "Additional CN analysis of SRY in the 61 tumor matched blood samples revealed that only three tumor–blood pairs had deletions (CN ≤0.8) in both, indicating that SRY deletions are mainly tumor private." (PMID 33807423, 2021). "Thus, the tumor and its periphery harbor SRY-positive cells at higher levels than in normal breast tissue." (PMID 26808509, 2016). "In addition, the relative expression of the SRY gene had a median 5.5 times larger in the tumor than in its periphery (range, 1.1–389.4)." (PMID 26808509, 2016). "Interestingly, we observed that the SRY gene was found exclusively in the five remnant kidneys exhibiting WT rising questions whether the iPSs used as treatment may have acted as tumor-initiating cells leading to the WT formation." (PMID 28845162, 2017). "The downregulation of miR-126 significantly inhibited tumor growth in HBs and reduced the proportion of CD44+ CD90+ CD133+ cells, increasing the expression of IL-6, Oct4, SRY, TGF-β, and β-catenin in mouse tumor tissues." (PMID 41393242, 2025). "While SRY itself is not consistently associated with the tumor immune microenvironment, its expression changes may reflect indirect involvement in DNA repair or immune evasion processes, potentially mediated via epigenetic modifications or interaction with other transcriptional regulators." (PMID 41012596, 2025). "It's interesting that FATS is a tumor suppressor highly expressed in testis, which is likely to be mediated by a transcriptional activator SRY (sex-determining region Y)." (PMID 20843368, 2010). "In addition, the miR-126 inhibitor obviously decreased the ratio of CD44+ CD90+ CD133+ cells, as well as the levels of IL-1α, SRY, Oct4, IL-6, and TGF-β in tumor tissues of mice." (PMID 34746322, 2021).
tumor (continued). "However, it is unknown whether the SRY/Sox proteins have a similar function as Rox1 in the production of ceramides and PP2A activation in human cells, where this metabolic pathway is important for tumor suppression by mediating apoptosis or growth inhibition." (PMID 39915438, 2025).
genetic disease (2 papers, 2017 to 2024). "If validated in a larger cohort, detection of SRY gene may prove to be a useful method to screen Y-linked genetic disease." (PMID 28978073, 2017). "For sex-linked inherited diseases, we performed a sex-identification test for embryos by PCR amplifying the SRY gene-specific sequences on the Y chromosome (data not shown)." (PMID 38306523, 2024).
neurodevelopmental disorder (2 papers, 2018 to 2021). A behavioral and cognitive disorder with onset during the developmental period that involves impaired or aberrant development of intellectual, motor, or social functions. "Whilst other Y-linked genes, such as neuroligin 4, will also need to be examined for their role in male-biased neurodevelopmental disorders, these results highlight the need to better understand the molecular regulation, function, and targets of SRY in the healthy and diseased male brain." (PMID 30104506, 2018).
SRY also shares sentences with these, for which no sentence is quoted: atherosclerosis (2 papers); colorectal cancer (2); fatty liver disease (2); Hypergonadotropic hypogonadism (2); hypogonadism (2); infection (2); testicular dysgenesis syndrome (2); Alpha-thalassemia (1); androgen excess (1); autoimmune thyroid disease (1); benign prostatic hyperplasia (1); bronchopulmonary dysplasia (1); campomelic dysplasia (1); cardiac hypertrophy (1); CHARGE syndrome (1); cholestasis (1); chromosomal Disorders of Sex Development (1); colon cancer (1); cryptorchidism (1); depression (1); freemartinism (1); glioblastoma (1); Gynecomastia (1); head and neck cancer (1); head and neck squamous cell carcinoma (1); heart failure (1); Hepatic steatosis (1); Hirschsprung disease (1); intellectual disabilities (1); liver cancer (1).
A further 19 diseases each share a sentence with SRY in 1 paper.